RPL4 (ribosomal protein L4)
Description:
Component of the large ribosomal subunit. The ribosome is a large ribonucleoprotein complex responsible for the synthesis of proteins in the cell.
Synonyms: L4; uL4
Tractability: Small molecule: an approved drug acts on it; a structure with a bound ligand is known; a high-quality ligand is known. PROTAC: UniProt records ubiquitination sites on it; ubiquitination databases record sites on it; its protein half-life has been measured; a small molecule that binds it is known. Other modalities: a drug acting on it is in phase 2 or 3 trials.
Target class: Other cytosolic protein
Gene: Protein-coding gene on chromosome 15 (66,498,015 to 66,524,532, reverse strand). Ensembl gene ENSG00000174444.
Subcellular location: Cytoplasm
Subcellular location (Human Protein Atlas): Cytosol; Endoplasmic reticulum; Nuclear bodies; Nucleoli
Pathways (Reactome):
Metabolism of proteins: Eukaryotic Translation Termination; Formation of a pool of free 40S subunits; GTP hydrolysis and joining of the 60S ribosomal subunit; L13a-mediated translational silencing of Ceruloplasmin expression; PELO:HBS1L and ABCE1 dissociate a ribosome on a non-stop mRNA; Peptide chain elongation; Ribosome Quality Control (RQC) complex extracts and degrades nascent peptide; SRP-dependent cotranslational protein targeting to membrane; ZNF598 and the Ribosome-associated Quality Trigger (RQT) complex dissociate a ribosome stalled on a no-go mRNA
Metabolism of RNA: Major pathway of rRNA processing in the nucleolus and cytosol; Nonsense Mediated Decay (NMD) enhanced by the Exon Junction Complex (EJC); Nonsense Mediated Decay (NMD) independent of the Exon Junction Complex (EJC)
Cellular responses to stimuli: Response of EIF2AK4 (GCN2) to amino acid deficiency
Developmental Biology: Regulation of expression of SLITs and ROBOs
Disease: Viral mRNA Translation
Metabolism: Selenocysteine synthesis
Gene Ontology:
Molecular function: protein binding; RNA binding; structural constituent of ribosome
Biological process: cytoplasmic translation; negative regulation of myoblast fusion; spermatogenesis; striated muscle contraction; translation
Cellular component: cytoplasm; cytosol; cytosolic large ribosomal subunit; cytosolic ribosome; extracellular exosome; focal adhesion; membrane; nucleolus; nucleus; ribonucleoprotein complex; rough endoplasmic reticulum; ribosome
Genetic constraint (gnomAD): Loss-of-function variants: 4 observed, 49.63 expected, observed/expected ratio (o/e) 0.0806, 90% interval 0.039 to 0.18. The upper end of that interval is the gene's LOEUF score, 0.18, which puts it in group 1 of 6, group 1 being the genes least tolerant of losing a copy. Missense variants: 413 observed, 560.79 expected, observed/expected ratio (o/e) 0.74, 90% interval 0.68 to 0.8. Synonymous variants: 208 observed, 184.88 expected, observed/expected ratio (o/e) 1.12, 90% interval 1 to 1.26.
Homologues: Orthologues: chimpanzee RPL4 (100% identical), macaque RPL4 (99% identical), dog RPL4 (95% identical), pig RPL4 (95% identical), mouse Rpl4 (93% identical), guinea pig RPL4 (91% identical), rat Rpl4-ps1 (81% identical), tropical clawed frog rpl4 (78% identical), zebrafish rpl4 (72% identical), Drosophila melanogaster RpL4 (61% identical), Caenorhabditis elegans rpl-4 (48% identical).
Diseases named in the same sentence as RPL4 in open-access papers:
RPL4 is named in the same sentence as 32 diseases in open-access papers, as found by Europe PMC text mining. Sharing a sentence is not in itself a finding about the gene and the disease. The quoted sentences say what the papers report.
COVID-19 (4 papers, 2022 to 2024). A disease caused by infection with severe acute respiratory syndrome coronavirus 2. "Accordingly, translation activity was also measured by the expression of RPL4 marker that was significantly induced in PBMC from COVID-19 patients accordingly with the ER activity and modulated under MLN4924 induction." (PMID 35831294, 2022). "By comparing the upregulated genes between COVID-19 patients and recovered individuals, we found that 21 genes (i.e., RPL4, MT-ND2, SCD5, MT-CYB, EZR) were shared between the conditions." (PMID 36059456, 2022). "In addition, we found a positive correlation between the COVID-19-related protein RPL4 and JOA." (PMID 35720320, 2022). "Also, spec_24h mRNAs were enriched in 12 KEGG terms such as Coronavirus disease-COVID-19, Ribosome, MAPK signaling pathway, Cytokine-cytokine receptor interaction, Focal adhesion, involving genes such as Rpl7, Rpl3, Rpl5, Rpl4, Rps15a." (PMID 38622534, 2024).
viral infection (3 papers, 2020 to 2024). "In our experiment, in all treatment options with inducers of resistance, lack of moisture, and viral infection, there was a significant decrease in the content of RPL4 relative to the control." (PMID 39204646, 2024). "Conversely, the protease required for viral entry, TMPRSS2, was reduced upon viral infection but was not modulated by viral dose, nor were ribosomal proteins (RPL4, RPS6)." (PMID 32898168, 2020).
malignant ovarian tumours (2 papers, 2013 to 2021). "We found IPO8 and RPL4 to be suitable reference genes for normalization of target gene expression in benign, borderline, and malignant ovarian tumours." (PMID 24001041, 2013). "In conclusion, thorough statistical evaluation of our 13 candidate RGs identified IPO8 followed by RPL4 as the most suitable for the normalization of gene expression data in benign, borderline, and malignant ovarian tumours." (PMID 24001041, 2013).
babesiosis (1 paper, 2017). Babesiosis refers to a condition caused by microscopic parasites that infect the red blood cells. "A recent study identified variants in cytb and rpl4 that were associate with relapsing babesiosis, but parasites often utilize various mechanisms for drug resistance." (PMID 29075254, 2017).
breast carcinoma (1 paper, 2025). "Moreover, we also showed that the expression level of RPL4 was significantly related to the survival of breast cancer patients." (PMID 41263459, 2025).
breast tumor (1 paper, 2025). "Taken together, these results indicate that RPL4 can interact with ZC3H12D and affect the ability of ZC3H12D to destabilize cell cycle‐promoting mRNAs in human breast tumor cells." (PMID 41263459, 2025). "Ribosomal protein L4 (RPL4) was shown to interact with ZC3H12D and facilitate the degradation of the CCND1 mRNA in breast tumor cells." (PMID 41263459, 2025).
enteritis (1 paper, 2011). Inflammation of the small intestine. "RPL4, HPRT1 and B2M are reported as stably expressed and suitable candidate genes in intestinal tissues collected from healthy pig and from pigs with enteritis." (PMID 22023805, 2011).
epilepsy (1 paper, 2025). A brain disorder characterized by episodes of abnormally increased neuronal discharge resulting in transient episodes of sensory or motor neurological dysfunction, or psychic dysfunction. "In contrast, some genes (RPL4, MTPAP, and SNX30) that are downregulated in the PZ also showed downregulation in epilepsy samples in the TLE versus healthy scRNA dataset." (PMID 39541170, 2025).
Epstein-Barr virus infection (1 paper, 2024). An infection that is caused by Epstein-Barr virus. "During Epstein Barr Virus infection, upregulation of RPL4 expression and its nuclear relocalization facilitate the formation of a ternary complex with Nuclear Antigen 1 (EBNA1) and NCL, promoting persistent infection." (PMID 39100766, 2024).
glioblastoma (1 paper, 2019). The most malignant astrocytic tumor (WHO grade IV). "Moreover, to investigate the reliability and the integrity of our NGS transcription data results for each compartment, we evaluated the expression of genes considered as housekeeping candidates in human normal brain tissue, glioblastoma and endothelial cells (RPL13A, RPL4, CYC1, EIF4A2)." (PMID 31231613, 2019).
glioma (1 paper, 2022). A benign or malignant brain and spinal cord tumor that arises from glial cells (astrocytes, oligodendrocytes, ependymal cells). "But, the RT-qPCR results showed that five genes (IKBKB, PDIA4, RCC2, RPL4, and TXNIP) were low expressed in glioma cell lines compared to HA." (PMID 36111134, 2022).
liver cancer (1 paper, 2020). An epithelial or non-epithelial malignant neoplasm that arises from the liver. "LncRNA SNHG7 facilitates the mobility and invasive capacity of liver cancer cell via modulating miR-122-5p and Ribosomal Protein L4 (RPL4)." (PMID 32976115, 2020).
myocardial infarction (1 paper, 2017). Gross necrosis of the myocardium, as a result of interruption of the blood supply to the area, as in coronary thrombosis. "In the myocardial infarction (MI) model a significant increase in Fstl1 expression at one and two weeks after MI was found when normalizing the data with the validated reference genes Eef1e1 and Rpl4 (F = 6.348, p = 0.011)." (PMID 28154421, 2017).
tumor (11 papers, 2008 to 2025). "Ribosomal proteins (e.g., ribosomal protein L4, 5, 7a, 8, 9, 10, 10a, 11, 12, 13, 14, 18, 18a, 19, 23, 26, 27, 27a, 28, 32, 36, 37a, ribosomal protein S2, 4, 5, 6, 8, 11, 12, 13, 15a, 18, 19, 24, 25, 27, 31 and ribosomal protein P0 variant) are molecules important for tumor growth and survival." (PMID 19017389, 2008). "Studies indicated that RPL4 participated in regulating tumor cell proliferation." (PMID 36111134, 2022). "Interfering with the interaction between PRDX2 and RPL4 may reverse the chemoresistance of tumor cells." (PMID 34117220, 2021). "Based on these criteria and supporting literature, HNRNPM, RPL4, and RPS4X were prioritized for further validation due to their reported involvement in tumor progression or chemoresistance." (PMID 40476445, 2025). "Expression of IPO8, RPL4, TBP, RPLPO, and ACTB had the least variation in expression across the tumour samples according to GeNorm, NormFinder, and BestKeeper." (PMID 24001041, 2013). "RPL4, RPLP0, and RPS6 are closely related to tumor growth and cell cycle control; this relationship indicates that they may contribute to the transcriptomic stability and survival of TICs." (PMID 40862733, 2025).
cancer (6 papers, 2011 to 2026). A tumor composed of atypical neoplastic, often pleomorphic cells that invade other tissues. "Ribosomal proteins RPS3 and RPL4, together with FBL (fibrillarin), contribute to ribosome biogenesis, rRNA processing, and translation, linking this module to the increased protein synthesis demands of rapidly proliferating cancer cells." (PMID 41514860, 2025).
infection (5 papers, 2016 to 2025). The state of being infected such as from the introduction of a foreign agent such as serum, vaccine, antigenic substance or organism. "In addition, we validated the relative expression of some of the Rpl and Rps transcripts by RT-PCR and found the significantly lowered expression of Rpl4, Rpl12, Rps18, Rps19 during the infection compared to naïve animals." (PMID 35789215, 2022). "Previous studies comparing untreated HIV-infected individuals to healthy controls reported decreased expression of several ribosomal proteins, such as RPS27, RPL18A, RPL8, RPL26, RPL4, and RPS21, possibly reflecting impaired translational activity during active infection." (PMID 41226717, 2025).
neurodegenerative disease (2 papers, 2022 to 2025). A disorder of the central nervous system characterized by gradual and progressive loss of neural tissue and neurologic function. "UBC, RPL4, and HSPA1A were identified as common hub genes, indicating their central role in the intersected network of dysregulated astrocytic genes across multiple neurodegenerative diseases." (PMID 40244314, 2025).
RPL4 also shares sentences with these, for which no sentence is quoted: HCMV infection (2 papers); ovarian tumors (2); bacterial infection (1); benign tumours (1); colon cancer (1); colorectal cancer (1); Diamond-Blackfan anaemia (1); hepatoma (1); leukemia (1); lymphoma (1); ovarian carcinoma (1); pancreatic cancer (1); parasitic infections (1); sunburn (1); Williams syndrome (1).